ENSG00000238707
Synonyms: LOC124900300
Gene: Small nucleolar RNA gene on chromosome 10 (56,595,963 to 56,596,031, reverse strand). Ensembl gene ENSG00000238707.
Gene Ontology:
Biological process: RNA processing
Cellular component: nucleolus
Homologues: Paralogues in human: SNORD2 (83% identical).